VHRT (ventricular heart development associated lncRNA)
Synonyms: MASCC1; RP1-46F2.2; LINC01405
Gene: Long non-coding RNA gene on chromosome 12 (110,934,267 to 110,973,930, forward strand). Ensembl gene ENSG00000185847.
Diseases named in the same sentence as VHRT in open-access papers:
VHRT is named in the same sentence as 10 diseases in open-access papers, as found by Europe PMC text mining. Sharing a sentence is not in itself a finding about the gene and the disease.
VHRT shares sentences with these, for which no sentence is quoted: tumor (2 papers); breast carcinoma (1); cancer (1); cervical cancer (1); esophageal carcinoma (1); head and neck squamous cell carcinoma (1); hepatocellular carcinoma (1); lung carcinoma (1); MELAS (1); rotator cuff tears (1).